SERPINA2 (serpin family A member 2 (gene/pseudogene))
Description:
Putative serine protease inhibitor.
Synonyms: ARGS; ATR; PIL; SERPINA2P; psiATR
Gene: Protein-coding gene on chromosome 14 (94,364,316 to 94,366,698, reverse strand). Ensembl gene ENSG00000258597.
Subcellular location: Endoplasmic reticulum
Homologues: Orthologues: macaque SERPINA2 (92% identical), rat Serpina1fl2 (42% identical), mouse Serpina1f (36% identical), rat Serpina1f (35% identical). Paralogues in human: SERPINA1 (59% identical), SERPINA3 (36% identical), SERPINA4 (35% identical), SERPINA11 (35% identical), SERPINA6 (34% identical), SERPINA9 (34% identical), SERPINA5 (33% identical), SERPINA7 (31% identical), SERPINA10 (27% identical), SERPINA12 (27% identical), SERPINB9 (24% identical), SERPINB4 (24% identical), and 24 more.
Diseases named in the same sentence as SERPINA2 in open-access papers:
SERPINA2 is named in the same sentence as 11 diseases in open-access papers, as found by Europe PMC text mining. Sharing a sentence is not in itself a finding about the gene and the disease. The quoted sentences say what the papers report.
substance abuse (1 paper, 2022). The use of a drug for a reason other than which it was intended or in a manner or in quantities other than directed. "This peak includes candidate genes, such as SERPINA1 and SERPINA2 (serine-peptidase inhibitor, clade A, members 1 and 2), which were previously implicated in a GWAS for substance abuse vulnerability." (PMID 35629112, 2022).
SERPINA2 also shares sentences with these, for which no sentence is quoted: dementia (5 papers); cognitive decline (2); breast carcinoma (1); cancer (1); colorectal cancer (1); Headache (1); infarcts (1); major depression (1); migraine (1); prostate carcinoma (1).